EPO (erythropoietin)
Diseases named in the same sentence as EPO in open-access papers (continued):
Sharing a sentence is not in itself a finding about the gene and the disease.
anemia (continued). "Functional iron deficiency due to chronic inflammation, decreased erythropoietin production due to renal dysfunction, gastrointestinal bleeding, and fluid dilution all contribute to anemia through complex interactions." (PMID 38256345, 2024). "EPO therapy is paramount in conditions marked by endogenous EPO production deficiency, such as chronic kidney disease, fostering red blood cell production stimulation and alleviating anaemia burdens." (PMID 39184703, 2024). "There are various factors that cause anemia, such as tumor extension into bone marrow, chemotherapy, and deficiency of iron, vitamin, and erythropoietin." (PMID 39286026, 2024). "The pathophysiology of anemia in CKD involves the interplay of various factors such as erythropoietin (EPO) deficiency, iron dysregulation, chronic inflammation, bone marrow dysfunction, and nutritional deficiencies." (PMID 38927397, 2024). "IL-1β associated with reduced EPO synthesis and blockade of IL-1β is associated with reduced incidence of anemia and improvement of hemoglobin levels." (PMID 38675885, 2024). "It has been suggested that a progressive decline in endogenous EPO level is associated with the development of anaemia in CKD." (PMID 39682316, 2024). "Based on a large amount of clinical and basic research data, patients with heart failure are more likely to have combined anemia, of which the most important pathophysiological mechanisms are iron deficiency and insufficient erythropoietin synthesis." (PMID 38402548, 2024). "In CKD, anemia, linked to reduced erythropoietin production, contributes to cardiovascular risk by promoting markers of endothelial activation and left ventricular hypertrophy." (PMID 38675885, 2024). "Despite commendable advances in anemia treatment, concerns regarding the potential association between EPO administration and an elevated risk of bone loss or fractures are growing." (PMID 39835325, 2024). "While EPO therapy in SCA holds great promise in addressing the chronic anaemia and associated complications, it also presents several challenges and considerations that need to be carefully managed." (PMID 38463100, 2024). "Anemia and hypoxia are common adverse events associated with HIF2α inhibitors, with anemic patients requiring exogenous erythropoietin therapy and patients with respiratory distress requiring oxygen therapy." (PMID 38390305, 2024). "In HD patients with ISD, anemia generally worsens, due to the diminished response to erythropoietin administration, caused by inflammation." (PMID 38534719, 2024). "Anaemia is linked to periodontitis as certain inflammatory cytokines produced during periodontal inflammation can depress erythropoietin production leading to the development of anemia." (PMID 39040750, 2024). "Nonetheless, the significance of osteoblastic EPO in aging, bone regeneration, and its therapeutic potential, particularly in treating anemia associated with chronic kidney disease, warrants additional investigation." (PMID 38764792, 2024). "Many clinical trials have evaluated the beneficial effects of EPO for treating anemia associated with renal failure." (PMID 39355466, 2024). "Reduced renal perfusion leads to renal ischemia, which in turn reduces erythropoietin levels, causing anemia." (PMID 39588122, 2024). "One of the hallmark complications of CKD is anemia, primarily due to decreased production of erythropoietin (EPO) by the damaged kidneys." (PMID 39200211, 2024). "Kidney disease is an important cause of anemia in patients with HF through multiple mechanisms, such as impairment of erythropoietin production by mesenchymal duct pericytes." (PMID 39624217, 2024). "One study describes normocytic/macrocytic anemia predominantly as a result of low EPO levels instead (one patient was cobalamin deficient and all had normal folate levels) in lung transplant recipients." (PMID 39211639, 2024).
anemia (continued). "People with advanced CKD commonly experience anemia, in part due to the loss of endogenous erythropoietin production from kidneys." (PMID 39124645, 2024). "Apart from iron supplements, recombinant erythropoietin (Epo) is also used for the treatment of IBD‐associated anemia, whereas side effects such as the increased risk of thromboembolic events, stroke, or cardiovascular disorders were observed in some patients." (PMID 38235606, 2024). "In fact, urinary losses of EPO have been shown to cause EPO-deficiency anemia and prevent the normal increase in plasma EPO level in response to anemia and hypoxia in nephrotic syndrome (NS)." (PMID 38393003, 2024). "Clinically, recombinant EPO is used to treat anemia caused by chronic kidney disease, cancer, or chronic blood loss." (PMID 39278948, 2024). "Decreased erythropoietin production is an important cause of the development of anemia in DM patients." (PMID 39347127, 2024). "The literature points to three possible physiological mechanisms that explain the association between anemia and vitamin D insufficiency: modulation of pro-inflammatory cytokines, regulation of hepcidin levels, and a reduced response to erythropoietin." (PMID 39519501, 2024). "Other factors including the degree of blood concentration, the causes and progression rate of anemia, as well as the drug usage including iron supplements and erythropoietin should also be considered when choosing the transfusion strategy." (PMID 38310116, 2024). "There are some approved drugs that stimulate erythropoiesis; one such drug is Epoetin Alfa (human erythropoietin), which is routinely used in the treatment of anemias associated with chronic kidney disease and cancer." (PMID 38731114, 2024). "Conversely, individuals with anemia demonstrated a lower rate of EPO increase, suggesting that anemia is linked to a failure in the normal compensatory rise of EPO levels during aging." (PMID 38610814, 2024). "Strikingly, Cd causes EPO hypoproduction in vivo, which contributes to anemia elicited by CLCE with CKD and suggests that REP cells in the peritubular interstitial space of the renal inner cortex are also damaged by Cd." (PMID 39256317, 2024). "The leading causes of renal anemia include deficiency of endogenous humanerythropoietin (EPO), iron deficiency, microinflammatory conditions, secondaryhyperparathyroidism, inadequate dialysis, and other causes of bleeding and anemia." (PMID 39076321, 2024). "Chronic inflammation from HIV infection adversely affects erythropoiesis, erythrocyte lifespan, and erythropoietin response, leading to a heightened risk of co-infections such as tuberculosis, persistent severe anemia, and increased mortality." (PMID 38675885, 2024). "All ESAs effectively correct CKD-associated anemia by replacing erythropoietin (EPO) deficiency occurring in failing kidneys." (PMID 38705934, 2024). "EPO determination is mainly a diagnosis of exclusion to identify, for example, chronic kidney disease as the cause of anemia." (PMID 38974321, 2024). "Although, in CKD patients, anemia is mainly caused by reduced erythropoietin levels, its onset has a multifactorial etiology." (PMID 39407717, 2024). "Recombinant human erythropoietin (rHuEPO) is commonly used to treat anemia associated with chronic kidney disease (CKD)." (PMID 38528249, 2024). "The advent of darbepoetin alfa (DPO) as a therapeutic alternative to recombinant human erythropoietin alpha (EPO) has revolutionized the management of CKD-associated anemia." (PMID 38313992, 2024). "In a CKD mouse model, FGF23 signaling inhibition improved anemia and iron deficiency by increasing EPO levels, hemoglobin, red blood cells, bone marrow erythroid progenitors, and driving hematopoietic stem cells to the erythroid lineage." (PMID 36831276, 2023). "Patients undergoing MHD are predisposed to anemia owing to factors such as reduced erythropoietin synthesis." (PMID 37077571, 2023).
anemia (continued). "In CKD, anemia results primarily from a relative deficiency in erythropoietin (EPO) production in the kidney that progressively worsens with lower GFR." (PMID 38125882, 2023). "Women with erythropoietin > 75th percentile during pregnancy exhibited a three-fold greater risk of anemia, suggesting that erythropoietin is a sensitive predictor of anemia at delivery." (PMID 37764830, 2023). "Patients with iron deficiency anemia should receive replacement therapy, and, in the case of low erythropoietin levels, therapy with erythropoietin should be considered." (PMID 37606426, 2023). "Erfe is upregulated in erythroid tissues in all conditions characterized by increased serum EPO and expanded erythropoiesis, such as iron deficiency anemia and hypoxia, but also in diseases characterized by ineffective erythropoiesis, such as beta-thalassemia." (PMID 36835406, 2023). "Intravenous or subcutaneous erythropoiesis-stimulating agents (ESAs) are advised to treat CKD-associated anemia, since shortage of erythropoietin (EPO) and iron is the main cause of anemia." (PMID 36724056, 2023). "Severe iron deficiency affects healthy erythropoietin-mediated erythropoiesis and causes anaemia: a reduction in haemoglobin concentration and red blood cell count." (PMID 37686128, 2023). "In patients who initiated dialysis, the use of erythropoietin-stimulating agents significantly improved nerve conduction, and in pediatric patients with iron deficiency anemia, peripheral neuropathy was observed to reverse after iron treatment." (PMID 38202194, 2023). "Deletion of EPO or EPOR leads to embryonic lethality at approximately E13 due to severe anemia associated with defects in definitive erythropoiesis in mice." (PMID 37578340, 2023). "It is also possible that HIV infection causes anemia through changes in cytokine production, altered erythropoietin response to bone marrow, and the utilization of antiretroviral drugs, particularly zidovudine." (PMID 37081836, 2023). "The underlying mechanisms of RBC dysfunction and anemia in DM are multifactorial in nature, with reduced erythropoietin (EPO) production being a commonly cited cause of anemia across various glomerular filtration rates." (PMID 37606388, 2023). "Borrowing on the experience of end-stage chronic kidney disease, roxadustat is now under evaluation for the treatment of anemia of lower-risk MDS with baseline EPO levels below 400 IU/L (NCT03263091)." (PMID 36574201, 2023). "The pathogenesis of CKD-related anemia includes iron deficiency, insufficient erythropoietin production, erythropoietin hypo-responsiveness, decreased RBC half-life, and chronic inflammation." (PMID 36674173, 2023). "Anemia is caused by multifactorial factors such as chronic inflammation, renal dysfunction, and erythropoietin resistance." (PMID 37999260, 2023). "Although anemia is associated with increased risk, intensive anemia treatment with erythropoietin (EPO) and subsequently with other erythropoiesis-stimulating agents (ESA) is of limited usefulness." (PMID 37763045, 2023). "Renal failure, in which EPO production is reduced, and the presence of proteinuria with possible loss of transferrin and EPO represent other causes of anemia." (PMID 37374094, 2023). "Yan and Xu summarised the pathophysiology of the inflammatory cytokines that cause anaemia and EPO resistance." (PMID 37623232, 2023). "Chronic inflammatory activity, elevated levels of advanced glycation end products (AGEs), hyporesponsiveness to erythropoietin, the effects of oxidative stress, and anti-diabetic medicines are also other possible causes of anemia in DM patients." (PMID 36730249, 2023). "The correction of anemia currently relies on use of intravenous erythropoiesis‐stimulating agents and iron administration, however, recombinant human EPO and its analogues have been associated with increased risk of adverse cardiovascular events." (PMID 37885335, 2023).
anemia (continued). "Meanwhile, iron deficiency anemia, blunted erythropoietin synthesis/response, and guideline-recommended treatments are assumed to be the most significant underlying factors responsible for the inception and exacerbation of anemia in HF patients." (PMID 37794317, 2023). "The effect of high urea on insulin resistance is mediated by a decrease in erythropoietin production by uremic toxins causing anemia." (PMID 36994079, 2023). "This study assessed the presence of anti-EPO antibodies and their association with anaemia in Plasmodium falciparum-infected pregnant women." (PMID 36989322, 2023). "These agents, which favorably affect prognosis both in CKD and HF, increase hemoglobin by approximately 0.6–0.7 g/dL, an effect that has been linked to a rise in EPO and an expansion in red blood cell mass that alleviate anemia." (PMID 37763045, 2023). "As mentioned in the introduction, anemia can be attributed to two primary causes: iron deficiency and impaired kidney function leading to insufficient production of EPO." (PMID 37960326, 2023). "The use of erythropoietin in treating moderate anemia associated with heart failure can beneficially affect cardiac function, improving both NYHA functional class and LVEF, decreasing atrial natriuretic peptide values, and improving kidney function." (PMID 36673114, 2023). "Considering that neuropathy is common in patients with poor glycemic control, one of the reasons for the increased risk of anemia is impairment of production and release of the erythropoietin stimulated by the autonomic nervous system." (PMID 36894956, 2023). "CKD anemia is a multifactorial condition caused by erythropoietin (EPO) deficiency, uremia-induced erythropoiesis inhibition, erythrocyte’s decreased longevity, and iron homeostasis dysregulation." (PMID 38022248, 2023). "Decreased erythropoietin (EPO) synthesis and abnormal iron metabolism caused by inflammation are important contributors to anemia in patients with CKD." (PMID 38017482, 2023). "Our findings show that EPO levels are decreased in AI or AUE while increased in bone marrow disease-associated anemia, suggesting its role in differentiating bone marrow disease in elderly anemic patients with unclear etiology." (PMID 37741889, 2023). "In β-thalassemia, anemia drives erythropoietin production, which in turn causes massive expansion of erythroid precursors in the marrow and elsewhere." (PMID 35905974, 2023). "Recently, new treatments have offered additional options for the management of erythropoietin (EPO) deficiency anaemia in relation to CKD." (PMID 37623232, 2023). "A similar finding was observed in a previous study involving patients suffering from systemic lupus erythematosus, which suggested significant association between anti-EPO antibodies and anaemia." (PMID 36989322, 2023). "Other well‐known causes of anemia include chronic kidney disease, decreased erythropoietin secretion, reduced response to erythropoietin, inflammatory processes, bone marrow failure conditions, and polypharmacy." (PMID 36960478, 2023). "But some factors contribute to CKD-related anemia and decreased responsiveness to EPO, such as iron deficiency, inflammation, solutes, and uremic toxins." (PMID 37390095, 2023). "Chronic Kidney Disease (CKD) which involves gradual loss of kidney function is characterized by low levels of a glycoprotein called Erythropoietin (EPO) that leads to red blood cell deficiency and anemia." (PMID 37919778, 2023). "The etiology of anemia, which presents itself as normochromic and normocytic, is not only traced to erythropoietin deficiency." (PMID 37375619, 2023). "Allowing hemodialysis patients to take low doses of oral vitamin C effectively reduces erythropoietin dose requirements and improves anemia in functional iron-deficient patients." (PMID 36839219, 2023).
anemia (continued). "This subtype of anemia occurs due to functional iron deficiency caused by different pathophysiological mechanisms, such as excess hepcidin production, suppressed erythropoietin production and reduced lifespan of red blood cells." (PMID 37510716, 2023). "Studies have reported that anaemia in CKD mainly results from impaired production of erythropoietin by the failing kidneys and anaemia is significantly associated with increased odds for CKD, CKD progression and worse clinical outcomes." (PMID 36780543, 2023). "In AI, HMGB1 disrupts the signal transduction of erythropoietin (EPO), causing prolonged anemia after sepsis recovery." (PMID 37223096, 2023). "The two primary FDA-approved indications for erythropoietin stimulating agents (ESA) use include anemia due to CKD and anemia caused by chemotherapy in cancer patients." (PMID 38029231, 2023). "The reduction in RBCs and Hb in arthritic rats resulted in anemia, which is caused by erythrocyte disruption, bone marrow failure, and decreased erythropoietin." (PMID 37893036, 2023). "It is mainly indicated for the management of anemia caused by either EPO deficiency/insufficiency or resistance in different clinical settings such as chronic kidney disease (CKD), congestive heart failure, chemotherapy, and HIV." (PMID 38029231, 2023). "Paleness in dialysis patients can be ascribed to anemia due to decreased renal erythropoietin production as well as blood loss during dialysis." (PMID 38024163, 2023). "Anemia in HF patients is multifactorial and can result from functional iron deficiency due to chronic inflammation, low erythropoietin production that occurs from the cardio-renal syndrome, and a tendency for bone marrow unresponsiveness." (PMID 37448382, 2023). "This includes methods such as the use of pediatric phlebotomy tubes to minimize blood loss from laboratory testing, and the treatment of anemia through agents like iron and erythropoietin." (PMID 37624779, 2023). "The potential for erythropoietin to improve EB-associated anemia has also been explored in a few small studies where it (or an analogue, darbepoetin alfa) was administered along with intravenous iron." (PMID 36823529, 2023). "A recent trial of 505 patients with iron deficiency or anaemia undergoing cardiac surgery investigated the effects of ultra short-term treatment using a combination of iron, erythropoietin, vitamin B12, and folic acid." (PMID 37005650, 2023). "In the Epo-TAgh transgenic mouse-induced severe anemia due to a disrupted EPO encoding gene had developed renal dysfunction due to the exhibited renal hypoxia." (PMID 38022248, 2023). "The primary causes of the anemia associated with CKD are decreased erythropoietin (EPO) production and poor iron homeostasis, which result in diminished erythropoiesis." (PMID 38021836, 2023). "This review discusses the treatment of erythropoietin (EPO) deficiency anaemia and resistance in cases of chronic kidney disease (CKD)." (PMID 37623232, 2023). "CKD is associated with anemia due to decreased erythropoietin secretion and results in decreased oxygen supply, increasing cardiovascular risks." (PMID 37795473, 2023). "After CKD-associated anemia, the most common indications of EPO were anemia of chronic disease (38.3%) and chemotherapy-induced anemia (5.7%)." (PMID 38029231, 2023). "We found that the sFas/eGFR and EPO/Hb ratios at baseline were higher in patients with long-term anemia, suggesting that sFas is associated with EPO hyporesponsiveness." (PMID 37390095, 2023). "The major stimulus for EPO production and the increase is diminished arterial oxygen content associated with anemia or hypoxia." (PMID 37117600, 2023). "SENP1−/− embryos die at midgestation due to severe fetal anemia stemming from deficient erythropoietin production." (PMID 37468105, 2023). "The second pathogenic factor in anemia of inflammation is the reduced EPO level and progressive EPO resistance of bone marrow erythroid progenitors." (PMID 37240288, 2023).